IL7R (interleukin 7 receptor)
Diseases named in the same sentence as IL7R in open-access papers (continued):
Sharing a sentence is not in itself a finding about the gene and the disease.
Sepsis (continued). "The results showed the expression level of CD3D, CD3E, CD4, CD28, IL7R, and LCK was statistically different between sepsis and normal groups." (PMID 37113759, 2023). "The lower expression of the six hub genes (CD28, CD3D, CD4, IL7R, LCK, and CD3E) was observed in sepsis samples." (PMID 37113759, 2023). "In summary, endogenous IL-7 and IL-7R levels can be elevated in sepsis; however, this does not reverse the dysfunction and depletion of immune cells, even when accompanied by other decompensatory changes." (PMID 41158471, 2025). "Although the half-life of mRNA has a significant impact on protein formation, it does not affect the conclusion of the data analysis in this article that IL7R, GZMA and CD8A may serve as the attractively potential molecular biomarkers for sepsis." (PMID 39654893, 2024). "Moreover, lncRNA EGO and lncRNA HOTAIR myeloid-specific 1 arrived their peaks at 3 hours, while lncRNA IL7R arrived its peak at 24 hours in sepsis model, which suggested that lncRNAs could be ideal biological indicators for diagnosing and distinguishing different stages of sepsis in the future." (PMID 34630395, 2021). "Therefore, the disruption of IL-7/IL-7R signalling during confirmed LOS has potentially detrimental implications for regulation of immune and cellular homeostasis that contributes to sepsis pathophysiology." (PMID 32479514, 2020). "The change in receptor expression pattern that we observed over the course of sepsis, increased TIM-3, LAG-3 and CD69 with decreased IL-7R expression, is consistent with the phenotype of immune cell exhaustion, although the functional impairment was not as severe." (PMID 22742734, 2012). "Given the intricate and variable nature of sepsis, depending solely on IL-7 or IL-7R may not adequately reflect the disease’s multifactorial nature." (PMID 41158471, 2025). "However, IL7R, GZMA and CD8A may serve as the attractively potential molecular biomarkers for sepsis." (PMID 39654893, 2024). "Although CD4+ and CD8+ T cells express the IL-7R at similar levels, we found that the beneficial effect of IL-7 treatment on T cell recovery was more pronounced for CD8+ T cells than for CD4+ T cells, which confirms and extends earlier reports on other sepsis models." (PMID 30730978, 2019). "The overall absence of membrane IL-7R regulation in patients strengthens the use of IL-7 in septic shock and is consistent with preliminary data in preclinical models of sepsis which showed the efficacy of this molecule in restoring sepsis-induced T-cell alterations." (PMID 30995946, 2019).
type 1 diabetes (31 papers, 2010 to 2025). "An SNP within the gene encoding the IL-7R chain was found to be associated with type 1 diabetes mellitus." (PMID 31623129, 2019). "Clinical trials in type 1 diabetes showed that appropriate dosages of systemic anti-IL-7R Ab treatment selectively inhibited memory T cells while preserving naive T cells or regulatory T cells (Treg), as well as protective memory from past vaccinations." (PMID 40323267, 2025). "Others have described the intrinsic control of memory T-cells after IL-7R blockade in rodent models of type 1 diabetes through upregulation of PD-1 coinhibitory molecules." (PMID 30367166, 2018). "Efforts to translate pre-clinical studies showing efficacy of anti-IL-7Rα antibodies for the treatment of type 1 diabetes have been initiated in the clinic." (PMID 28356069, 2017). "Our previous studies showed that increased expression of the co-inhibitory receptor PD-1 in CD4+ TE/M cells from anti-IL-7Rα-treated NOD mice contributed to protection from type 1 diabetes." (PMID 28356069, 2017). "In this article, we discuss how the IL-7/IL-7R pathway can contribute to the development of type 1 diabetes and how preclinical models have demonstrated the efficacy of a selective targeting of this pathway." (PMID 26983628, 2016). "In contrast, transcripts that skip exon 6 (“C” allele of rs 6897932) confer susceptibility to type 1 diabetes and encode a soluble form of CD127 (sCD127), potentially altering the production of sCD127 and IL-7R signaling in T cells." (PMID 23970924, 2013). "We show colocalization of pQTLs for CTRB1, APOBR, IL7R, CPA1, and PNLIPRP1 with Type 1 diabetes GWAS signals, and Mendelian randomization causally implicates each of these five proteins in the aetiology of Type 1 diabetes." (PMID 40263317, 2025). "Genetic variation in and the expression of the IL7R gene, as well as increased expression of receptor/ligand genes, contribute to the pathogenesis of autoimmune and chronic inflammatory diseases such as type 1 diabetes and multiple sclerosis." (PMID 35907923, 2022). "Our results indicate that a broad program of immunoregulation underlies the slower disease kinetics afforded by IL-7Rα blockade in type 1 diabetes and, that markers of anti-IL-7Rα antibody activity can be detected in peripheral blood following a short course of treatment." (PMID 28356069, 2017). "Thus, a short treatment with blocking antibodies for IL-7Rα retains efficacy to delay and, in some cases, prevent diabetes progression, supporting continued efforts to translate anti-IL-7Rα antibodies for the prevention and treatment of type 1 diabetes." (PMID 28356069, 2017). "Therefore, we asked whether a treatment of limited duration with anti-IL-7Rα mAbs would retain benefit for long-term prevention of type 1 diabetes." (PMID 28356069, 2017). "We and others previously demonstrated that blocking IL-7 receptor alpha (IL-7Rα) prevented and reversed diabetes in non-obese diabetic (NOD) mice and hence has potential to be translated as an immunotherapy for human type 1 diabetes." (PMID 28356069, 2017).
lung carcinoma (30 papers, 2010 to 2025). "The association between IL-7R expression and patient prognosis has been investigated in breast cancer, pancreatic ductal adenocarcinoma, and lung cancer." (PMID 36672342, 2023). "Somatic mutations in IL7R have been identified in lung cancer patients where its functional significance is unknown, and mutations in IL7R are detected in 10% of pediatric T-ALL cases and in a few cases of pediatric B-ALL." (PMID 24678068, 2014). "Recently, we have found that TSLP, TSLPR, and IL-7Rα expression, examined by immunohistochemistry, was higher in the intratumoral lung cancer compared to the peritumoral area." (PMID 40873585, 2025). "TSLP, TSLPR, and IL-7Rα were overexpressed in intratumoral lung cancer. lfTSLP and sfTSLP were differently expressed in peritumoral and intratumoral lung cancer tissues." (PMID 40873585, 2025). "We also examined the expression of the two TSLP isoforms (lfTSLP and sfTSLP), TSLPR, and IL-7Rα mRNAs in peritumoral and intratumoral lung cancer." (PMID 40873585, 2025). "Serial section staining of IL7R and CD68 in colon-, stomach-, and lung cancers confirmed strong expression of IL7R in the macrophage compartment." (PMID 38424167, 2024). "These T cells appeared to resemble a recently described IL7R-HAVCR2+KRT86+DUSP4+LAYN+ subset, which has been associated with response to anti-PD1 therapy in lung cancer." (PMID 39312285, 2024). "Patients with PDAC had significantly higher IL-7R levels than did those with bile duct, stomach, liver, colon, and lung cancers." (PMID 35159120, 2022). "The Oncomine datasets showed the expression of IL7R in lung cancer tissues was decreased in all 13 datasets." (PMID 35264973, 2022). "Beyond hematological cancer, high expression of IL-7 and IL-7R in tumor tissues of breast and lung cancer patients is positively correlated with more aggressive breast cancers and poor survival." (PMID 34575268, 2021). "Lung cancer patients carrying IL-7R rs10213865 (AGAA haplotype) have higher lung adenocarcinoma risk." (PMID 34575268, 2021). "We evaluated the expression of TSLP, TSLPR, and IL-7Rα by immunohistochemistry in peritumoral and intratumoral areas of human lung cancer." (PMID 34440780, 2021). "The results of a typical experiment showed that the expression of TSLP, TSLPR and IL-7Rα was higher in the intratumoral area compared to peritumoral area of lung cancer." (PMID 34440780, 2021). "To confirm and extend the previous observation, we evaluated the expression of sfTSLP, lfTSLP, TSLPR, and IL-7Rα mRNAs in intratumoral and peritumoral areas of human lung cancer." (PMID 34440780, 2021). "Our results provide evidence, to our knowledge for the first time, that TSLP isoforms, TSLPR, and IL-7Rα were expressed in both intratumoral and peritumoral lung cancer tissues." (PMID 34440780, 2021). "Recent studies have identified other important targets of JQ1, such as FosL1 in lung cancer cell lines, or IL7R in lymphoblastic leukemia." (PMID 26397223, 2015). "Study on lung cancer cells provided evidence that IL-7/IL-7R is well correlated with VEGF and induce its upregulation." (PMID 24348676, 2013). "The aim of this study is to explore the expressions of IL-7 and IL-7R in lung cancer and the relationship between them with lymph node metastasis and prognosis in non-small cell lung cancer (NSCLC)." (PMID 21159243, 2010). "The expressions of IL-7 and IL-7R in 95 cases of NSCLC were detected with immunohistochemistry method and the relationship between IL-7 and IL-7R and their impact on lung cancer patients' outcomes were analyzed." (PMID 21159243, 2010). "Here authors show that mutation-associated neoantigen-specific CD8+ tumor-infiltrating lymphocytes can be recognized by MANAscore, an algorithm that uses weighted expression levels of CXCL13, ENTPD1 and IL7R in single-cell RNAseq datasets of lung cancer and melanoma patients as input." (PMID 39900903, 2025).
lung carcinoma (continued). "Studies on the impact of CXCR3 ligand in IL‐7/IL‐7Rα‐Fc–mediated antitumor activity revealed that when treating mice with lung cancer using IL‐7/IL‐7Rα‐Fc, it raised the levels of chemokine ligands CXCL9 and CXCL10, IFNγ, and IL‐12, but it reduced the levels of IL‐10 and TGF‐β." (PMID 39083441, 2025). "In addition, immunohistochemical expression of IL-7R in lung cancer patients was found to be an independent predictor of survival." (PMID 36672342, 2023). "TSLP, TSLPR, and IL-7Rα were expressed in intratumoral and peritumoral areas of human lung cancer." (PMID 34440780, 2021). "In the same study, it was demonstrated that macrophages purified from macroscopically normal lung parenchyma of patients with lung cancer constitutively express TSLP, TSLPR, and IL-7Rα." (PMID 40873585, 2025). "Overall, the results of these studies on IL-7R, ADAMTS12, and ADRB2 indicate their anti-tumor functions in lung cancer." (PMID 38808570, 2024). "Interleukin-7 receptor (IL7R) is the receptor of IL-7, and the IL-7/IL-7R interaction seems to have a two-sided effect in lung cancer." (PMID 35069695, 2021). "IL-7R is highly expressed in lung cancer and CRC and it promotes lung cancer vascular endothelial growth and metastasis." (PMID 28628609, 2017). "Because the distribution of mutations across a gene provides indications for its functional significance, we analyzed the distribution pattern of IL7R in pediatric ALL and lung cancer patients." (PMID 24678068, 2014). "Il7R and COL22A1 are related to the TME of lung cancer and breast cancer, respectively." (PMID 35813821, 2022).
breast cancer (28 papers, 2009 to 2025). A primary or metastatic malignant neoplasm involving the breast. "Several studies have found that IL-7R expression facilitates tumor progression; for example, high levels of IL-7R expression in lung and breast cancer tissues are associated with poor prognosis and tumor progression." (PMID 36672342, 2023). "The genes CXCL9, IL7R, CD79A, and CTSW were selected for their significant associations with overall survival (OS) and recurrence-free survival (RFS) in breast cancer patients." (PMID 40725191, 2025). "In the literature, elevated expression of CXCL9 and IL7R was related to an improved breast cancer prognosis." (PMID 40725191, 2025). "IL-7R is conventionally expressed in lymphocytes and detected in tumor cells, including lung and breast cancer." (PMID 40707961, 2025). "IL-7R has emerged as a potential prognostic marker in breast cancer patients, particularly in maintaining immunologically active states in the TME and promoting immune reconstitution." (PMID 41048344, 2025). "What is more, the dysregulated genes IL2RG, IL6R, IL7R and TGFB2 have been reported to be associated with metastasis site or prognosis, and CCR6 is associated with both live metastasis in breast cancer and bone metastasis in human neuroblastoma." (PMID 25163697, 2014). "Overexpression of IL7 and the IL7R correlates with invasion and poor prognosis in breast cancer." (PMID 38055067, 2023). "Results indicated that ATM and SEPP1 genes induced significant (p < 0.05) increased risk in BRCA-LumA patients than other type of breast cancer patients while GABARAP gene induced significant (p < 0.05) decreased risk in all BRCA patients, but IL7R in only BRCA-LumB patients." (PMID 34572798, 2021). "Meanwhile, other researchers have shown that the IL-7/IL-7R axis contributes to EMT in prostate cancer cells and breast cancer cells." (PMID 36672342, 2023). "In contrast, the receptors for IL7 (IL7R) and IL15 (IL15RA) were significantly overexpressed in basal B compared to luminal breast cancer cells." (PMID 38055067, 2023). "In fact, some immune related genes are essential in bone metastasis of breast cancer, and their family members, such as FAS, IL2RG and IL7R, have shown dysregulated in our work and have been reported to be either metastasis related or bone metastasis related." (PMID 25163697, 2014). "Through a combination of RNA sequencing analysis, database screening and invasion assays we identified IL7/IL7R and IL15/IL15R as pairs of chemokines and receptors with potential roles in promoting chemotactic migration of breast cancer cells with mesenchymal properties towards the lymphatics." (PMID 38055067, 2023). "Therefore, AREG+, IL7R+ and VCAM1+ innate lymphoid cells can help determine prognosis for breast cancer patients." (PMID 36497286, 2022). "Analysis of CD107a and CD127 in PBMCs from patients with breast cancer showed a trend, but not statistically solid differences, towards lower values of IL-7R expression on CD4+CD107a+ T-cells." (PMID 19657390, 2009). "However, the IL7R and the IL15Ra were not induced during TGFβ1-induced EMT in NMuMG cells, suggesting that other signaling pathways drive the expression of these receptors in basal breast cancer cells." (PMID 38055067, 2023).
severe combined immunodeficiency (28 papers, 2006 to 2024). Severe combined immunodeficiency (SCID) comprises a group of rare monogenic primary immunodeficiency disorders characterized by a lack of functional peripheral T lymphocytes resulting in early-onset severe respiratory infections and failure to thrive. "IL7R deficiency is associated with severe combined immunodeficiency (SCID)." (PMID 35264973, 2022). "IL7R deficiency may be associated with severe combined immunodeficiency (SCID)." (PMID 38143258, 2024). "For example, IL7R-deficiency may contribute to severe combined immunodeficiency (SCID)." (PMID 33177245, 2020). "Mutations in the extracellular domain of IL-7Rα are associated with severe combined immunodeficiency (SCID) of the T− B+ NK+ type." (PMID 28484723, 2017). "Inactivating mutations of IL7R are associated with severe combined immunodeficiency (SCID)." (PMID 35294722, 2022). "Loss of function mutations in IL-7R leads to severe combined immunodeficiency (SCID)." (PMID 34540869, 2021). "On the other hand, very low IL7R signaling has been observed in severe combined immunodeficiency and in HIV infection." (PMID 26566388, 2015). "Another study showed that IL-7Rα mutations in humans result in severe combined immunodeficiency (SCID), which is characterized by the lack of T cells and normal numbers but dysfunctional B cells." (PMID 37266430, 2023). "The classical example is severe combined immunodeficiency (SCID) with defects in T cells, B cells, and NK cells caused by defects in IL2RG, RAG1/2, ADA, JAK3, and IL7R genes, in which an increased risk of disseminated VZV infection has been well-recognized for many years." (PMID 32495195, 2020). "In humans, mutations in the IL7Rα result in severe combined immunodeficiency (SCID) which is associated with the absence of T cells and normal numbers, nevertheless inactive, B cells." (PMID 32581241, 2020). "IL-7 is essential for T cell generation as IL-7- or IL-7R-deficient mice as well as IL-7Rα mutant patients with severe combined immunodeficiency (SCID) do not generate mature T lymphocytes." (PMID 30922400, 2019). "A human mutation in IL-7Rα results in a syndrome of severe combined immunodeficiency (SCID) with an absence of T cells." (PMID 25955647, 2015). "Dysfunction of IL7R has been detected in patients with severe combined immunodeficiency (SCID) leading to chronic inflammatory diseases." (PMID 30917529, 2019). "In particular, mutations of the IL7R α chain, or the γc chain, or its associated kinase, JAK3, are the major causes of human severe combined immunodeficiency (SCID)." (PMID 16907989, 2006). "Inactivation of IL-7 or IL-7R results in severe combined immunodeficiency (SCID)." (PMID 35581375, 2022). "Disrupting IL-7 signalling can result in profoundly impaired immunity as seen in patients with T-B+NK+ Severe Combined Immunodeficiency (SCID), a genetic defect that results in inactivation of the IL-7Rα signalling pathway." (PMID 21920046, 2011). "In humans, IL-7 receptor (IL-7R) paucity results in a complete lack of T cells, leading to severe combined immunodeficiency (SCID), but does not affect B-cell development." (PMID 36674902, 2023).